C1orf50 (chromosome 1 open reading frame 50)
Synonyms: MGC955
Tractability: PROTAC: ubiquitination databases record sites on it.
Gene: Protein-coding gene on chromosome 1 (42,767,245 to 42,779,491, forward strand). Ensembl gene ENSG00000164008.
Gene Ontology:
Molecular function: identical protein binding; protein binding
Genetic constraint (gnomAD): Loss-of-function variants: 17 observed, 16.87 expected, observed/expected ratio (o/e) 1.01, 90% interval 0.69 to 1.51. The upper end of that interval is the gene's LOEUF score, 1.51, which puts it in group 6 of 6, group 1 being the genes least tolerant of losing a copy. Missense variants: 244 observed, 205.16 expected, observed/expected ratio (o/e) 1.19, 90% interval 1.07 to 1.32. Synonymous variants: 89 observed, 82.12 expected, observed/expected ratio (o/e) 1.08, 90% interval 0.91 to 1.29.
Homologues: Orthologues: chimpanzee C1H1orf50 (99% identical), macaque C1H1orf50 (88% identical), guinea pig C1orf50 (87% identical), rabbit C1orf50 (86% identical), mouse AU022252 (84% identical), rat C5h1orf50 (82% identical), dog C1orf50 (81% identical), tropical clawed frog c7h1orf50 (64% identical), zebrafish C11H1orf50 (64% identical), Drosophila melanogaster CG31800 (35% identical), Caenorhabditis elegans C08B11.9 (34% identical).
Diseases named in the same sentence as C1orf50 in open-access papers:
C1orf50 is named in the same sentence as 4 diseases in open-access papers, as found by Europe PMC text mining. Sharing a sentence is not in itself a finding about the gene and the disease. The quoted sentences say what the papers report.
breast carcinoma (1 paper, 2025). "The data above shows that stage II breast cancer patients with high C1orf50 expression have a significantly worse prognosis." (PMID 39604563, 2025). "Bioinformatic analyses of the breast cancer dataset of TCGA, and in vitro analyses, reveal the molecular pathways influenced by C1orf50 expression." (PMID 39604563, 2025). "We have shown that C1orf50 expression levels are particularly detrimental to prognosis in a subset of patients with Luminal A stage II breast cancer." (PMID 39604563, 2025). "In breast cancer cell lines in which C1orf50 expression was knocked down by RNAi, cell proliferation was suppressed, and cancer stemness was significantly attenuated." (PMID 39604563, 2025). "Since stemness is generally assessed by self-renewal capacity, we evaluated C1orf50-depleted breast cancer cells and confirmed that C1orf50 expression is imperative to the self-renewal capacity in breast cancer cells." (PMID 39604563, 2025). "C1orf50 knockdown suppressed the cell cycle of breast cancer cells and weakened their ability to maintain the undifferentiated state and self-renewal capacity." (PMID 39604563, 2025). "In this study, we used biological, biochemical, and bioinformatic analyses to examine the role of C1orf50 in breast cancer progression." (PMID 39604563, 2025). "In contrast, the expression of C1orf50 protein was high in breast cancer tissues of all subtypes." (PMID 39604563, 2025). "Importantly, in immunostaining analysis of normal breast tissues and breast cancer tissues, the latter tended to show higher C1orf50 staining." (PMID 39604563, 2025). "Using the median of C1orf50 mRNA expression values, we divided stage II breast cancer patients into C1orf50-high and C1orf50-low groups and performed survival analysis of stage II breast cancer patients, finding a significant (p = 0.045) difference in 10-year survival." (PMID 39604563, 2025). "This study aims to elucidate the molecular role of C1orf50 in breast cancer progression." (PMID 39604563, 2025). "In the process of discovering new prognostic markers from genes of unknown function, we found that the expression of C1orf50 determines the prognosis of breast cancer patients, especially for those with Luminal A breast cancer." (PMID 39604563, 2025). "To elucidate the molecular mechanism by which C1orf50 mRNA expression affects Luminal breast cancer progression, we performed pathway analyses and found that the expression level of C1orf50 mRNA is highly correlated with cell cycle and cancer stemness-related factors." (PMID 39604563, 2025). "Upon analyzing data from The Cancer Genome Atlas-Breast Invasive Carcinoma (TCGA-BRCA) dataset, we discovered that C1orf50 is strongly correlated with the prognosis of stage II Luminal A breast cancer, which is considered to have low biological malignancy among ER-positive breast cancers." (PMID 39604563, 2025). "We found that C1orf50 may be a factor involved in survival in stage II breast cancer in postmenopausal patients." (PMID 39604563, 2025). "In addition, C1orf50 was found to be more abundant in breast cancer cells than in normal breast epithelium, suggesting C1orf50’s involvement in breast cancer pathogenesis." (PMID 39604563, 2025). "This suggests that the role of C1orf50 may be more specifically relevant to Luminal A subtype breast cancer." (PMID 39604563, 2025). "Our data suggests that C1orf50 progresses breast cancer stemness through YAP/TAZ signaling." (PMID 39604563, 2025). "The clinicopathological significance of C1orf50 is that it may aid in improving the prognosis of Luminal A breast cancer patients according to C1orf50 expression levels." (PMID 39604563, 2025). "Furthermore, immunostaining with anti-C1orf50 antibody in tissue arrays composed of normal mammary tissues and breast cancer tissues showed that C1orf50 protein expression was low in normal mammary tissue." (PMID 39604563, 2025). "This suggests that C1orf50 is essential for the maintenance of breast cancer stemness." (PMID 39604563, 2025).
breast carcinoma (continued). "Therefore, the expression level of C1orf50 may be a useful marker when considering the application of PD-L1 inhibitors in the Luminal breast cancer patient population." (PMID 39604563, 2025). "Next, we determined whether C1orf50 is expressed at the protein level in breast cancer cells." (PMID 39604563, 2025). "In addition, we investigated whether C1orf50 has different effects in premenopausal and postmenopausal breast cancer." (PMID 39604563, 2025). "Immunostaining with anti-YAP/TAZ, anti-C1orf50, and anti-NANOG antibodies in tissue arrays showed that C1orf50-high breast cancer cells express YAP/TAZ and NANOG at high levels in Luminal breast cancer cells." (PMID 39604563, 2025). "When comparing the expression levels of C1orf50 by IDC subtype, it was found that Luminal A breast cancer showed significantly higher expression levels of C1orf50 than non-Luminal A breast cancer." (PMID 39604563, 2025). "Our study uncovers the biological functions of C1orf50 in Luminal breast cancer progression, a finding not previously reported in any type of cancer." (PMID 39604563, 2025). "Using a cohort of breast cancer patients from the Clinical Proteomic Tumor Analysis Consortium (CPTAC), we analyzed whether C1orf50 mRNA and C1orf50 protein expression were correlated (r = 0.49, p < 0.001), and found a positive correlation." (PMID 39604563, 2025). "Therefore, further studies are warranted to explore the prognostic significance of C1orf50 in non-Luminal breast cancer subtypes, where differences may become more apparent with larger datasets." (PMID 39604563, 2025).
cancer (1 paper, 2025). A tumor composed of atypical neoplastic, often pleomorphic cells that invade other tissues. "To elucidate the molecular mechanisms of how C1orf50 promotes cancer progression, we performed pathway analysis focusing on C1orf50 mRNA expression levels using the TCGA-BRCA dataset." (PMID 39604563, 2025). "While searching for genes of unknown function that may be involved in cancer prognosis, Chromosome 1 Open Reading Frame 50 (C1orf50) exhibited a robust prognostic difference in melanoma patients according to the Human Protein Atlas." (PMID 39604563, 2025). "Our study is important because it is the first worldwide report on the role of a functionally unknown gene, C1orf50, in cancer progression." (PMID 39604563, 2025). "We confirmed that C1orf50 expression levels correlate with cancer stem cell-related signatures." (PMID 39604563, 2025). "The function of C1orf50 has not been previously reported, and its physiological and pathological roles and association with cancer biology remain completely unknown." (PMID 39604563, 2025).
C1orf50 also shares sentences with these, for which no sentence is quoted: triple-negative breast carcinoma (1 paper); Tumor (1).